SMAD2 (SMAD family member 2)
Diseases named in the same sentence as SMAD2 in open-access papers (continued):
Sharing a sentence is not in itself a finding about the gene and the disease.
hepatocellular carcinoma (continued). "We have previously shown that HDI-triggered EMT, invasion, and metastasis of hepatoma cells are mediated through inducing Snail's transcriptional expression via the Smad2/3 pathway." (PMID 32929346, 2020). "We confirmed that Galunisertib was able to inhibit TGF-β-induced Smad2 phosphorylation in our glioblastoma cell model, which is supported by previous studies in hepatocellular carcinoma." (PMID 29774119, 2018). "It has been demonstrated previously that HepG2 hepatoma cells are responsive to ActA: In these cells, treatment with exogenous rhActA leads to the phosphorylation of SMAD2, and this assay is thus suitable to measure the activity of ActA." (PMID 26950277, 2016). "Recently, it has been shown that FHL1, FHL2, and FHL3 physically and functionally interact with Smad2, Smad3, and Smad4, important regulators of cancer development and progression, and inhibit human hepatoma cell growth in vitro and in vivo." (PMID 24690879, 2014). "It has been demonstrated that FHL3 physically and functionally interact with Smad2, Smad3, and Smad4, important regulators of cancer development and progression, and inhibit human hepatoma cell growth in vitro and in vivo." (PMID 24690879, 2014). "We discovered that overexpressed TAT could increase the expression of cleaved caspase-9, but knocking down Smad2 could decrease cleaved caspase-9 level in hepatoma cell lines, so as Smad3 and Smad4." (PMID 38769521, 2024). "Western-Blot and Flow cytometry assays results suggested that Smad2/3/4 complex could active caspase-9 to improve hepatoma cell apoptosis through TAT." (PMID 38769521, 2024). "All these results suggest that Smad2/3/4 complex could active caspase-9 and induce hepatoma cell apoptosis through regulating TAT." (PMID 38769521, 2024). "Smad2/3/4 activated caspase-9 through regulating TAT to induce hepatoma cell apoptosis." (PMID 38769521, 2024). "Flow cytometry assay results showed that Smad2/3/4 complex could increase the apoptosis of hepatoma cells." (PMID 38769521, 2024). "There is a member of the PAK family, P21-activated kinase 3 (PAK3), a serine or threonine protein kinase, that could achieve Epithelial–mesenchymal transition (EMT) of hepatocellular carcinoma by regulating Smad2 and Smad3." (PMID 37505298, 2024). "Further, flow cytometry analysis results showed that overexpression of TAT could increase apoptosis of hepatoma cells and knocking down Smad2 could create a compensatory effect to decrease hepatoma cell apoptosis." (PMID 38769521, 2024). "In addition, it has been shown that FOXP1 can affect the activation of the TGF-β pathway by binding to the transcription factors Smad2 and Smad3, thereby causing CD8+ T cells de-lymphotoxicity in hepatocellular carcinoma tissues." (PMID 37035153, 2023). "BUB1 may promote proliferation of hepatocellular carcinoma cells by activating phosphorylation of SMAD2." (PMID 36479313, 2022). "Notably, lnc-UTGF promoted the TGF-β-stimulated migration of hepatoma cells, whereas this promoting effect was attenuated when SMAD2 and SMAD4 were knocked down." (PMID 34785655, 2021). "And we found that LY2109761 could inhibit cell proliferation by down-regulating the phosphorylation of Smad-2 as well as improved the therapeutic effect of TACE in a VX2 hepatocellular carcinoma model." (PMID 29416682, 2018). "In a loss of function study, FXR1 knockdown reduces hepatocellular carcinoma (HCC) cell invasion and migration via TGF-β modulation, whereas upregulation in HCC cells increases cell invasion which is abrogated by inhibiting SMAD2/3." (PMID 38238286, 2024). "Flow cytometry analysis showed that Smad2/3/4 complex could increase apoptosis of hepatoma cells." (PMID 38769521, 2024). "The CCK assay results showed that Smad2/3/4 complex could inhibit hepatoma cell proliferation." (PMID 38769521, 2024). "In addition, we found that Smad2/3/4 complex could active caspase-9 to induce hepatoma cell apoptosis through regulating TAT." (PMID 38769521, 2024).
hepatocellular carcinoma (continued). "Probably, Smad2/3/4 complex could active caspase-9 through TAT to induce hepatoma cell apoptosis." (PMID 38769521, 2024). "However, there have been many studies on miR-139-5p in the progression and mechanism of hepatocellular carcinoma, while there have been relatively few studies on miR-582-3p in this area; therefore, miR-582-3p/SMAD2 was selected for follow-up studies in this project." (PMID 35386287, 2022). "For example, TGF-β released from M2 macrophages promotes binding of Smad2/3 to the miR-362-3p promoter, resulting in upregulation of miR-362-3p in hepatocellular carcinoma (HCC) cells." (PMID 36114510, 2022). "Moreover, mutations in the SMAD2/4-binding sites abrogated the pro-migration effect of lnc-UTGF, suggesting that the pro-metastasis ability of lnc-UTGF in hepatoma cells mostly depends on its effect in increasing SMAD2/4 levels and enhancing the TGF-β/SMAD signaling." (PMID 34785655, 2021). "Human hepatocellular carcinoma (HCC) cells stably expressing a Smad2 mutant, in which the serine residues of the C-terminal SSXS motif were changed to alanine, demonstrated impaired Smad2 signaling and were resistant to growth inhibition by (exogenous) TGF-β." (PMID 33478130, 2021). "Accordingly, the Cyclin D1-dependent activation of Smad2/3 and Smad4 is also evidenced in hepatocellular carcinoma (HCC) patients and predicts disease progression." (PMID 33317149, 2020). "Here, we investigated the functional role of the cyclin D1-dependent activation of Smad2/3 and Smad4 in hepatocellular carcinoma (HCC) CSCs and in HCC primary tumors." (PMID 28415588, 2017). "Overexpression of CD44 is associated with low expression of E-cadherin, high expression of vimentin, a high percentage of phospho-Smad2 positive nuclei and poor prognosis in hepatocellular carcinoma (HCC) patients." (PMID 26985909, 2016). "TβRI stabilized downstream from TGF-β signaling causes the phosphorylation of Smad2 and 3, the transcription factors responsible for target gene induction, as verified by our result that USP4 fortified Smad2 phosphorylation and promoted migration and proliferation of hepatoma cell." (PMID 24798342, 2014). "However, FHL2 is frequently downregulated in hepatocellular carcinoma (HCC) and engages with Smad2-4 to regulate gene expression, ultimately inhibiting HCC cell proliferation." (PMID 40482916, 2025). "In hepatocellular carcinoma, farrerol inhibits transforming growth factor-β (TGF-β)-induced migration, invasion, and epithelial-mesenchymal transition (EMT) in hepatocellular carcinoma cells, and suppresses TGF-β-induced phosphorylation of Smad2/3." (PMID 41415563, 2025). "In hepatocellular carcinoma, miR-125b has an inhibitory effect on EMT and EMT-related features through SMAD2 and SMAD4, which are signal transducers of the TGFβ signaling pathway." (PMID 37443682, 2023). "A detailed further study is required to verify the interaction and crosstalk between the two TGF-β signaling pathways through Smad2/3 activation and Smad1/5/8 activation during EMT induction and metastasis of hepatoma cells." (PMID 35580109, 2022). "We selected 2 differentially expressed miRNAs (miR-139-5p and miR-582-3p) and four hub mRNAs (ACVR2B, SMAD2, SMAD5, and TGFBR3) for qRT-PCR verification in 20 hepatocellular carcinoma tissues and 20 adjacent tissues." (PMID 35386287, 2022). "The results showed that miR-139-5p and TGFBR3 were significantly down-regulated in hepatocellular carcinoma tissues, and miR-582-3p, ACVR2B, SMAD2 and SMAD5 were up-regulated in hepatocellular carcinoma tissues." (PMID 35386287, 2022). "In hepatocellular carcinoma, Foxp3 can suppress tumor progression via TGF-β/Smad2/3 signaling pathway." (PMID 35326661, 2022). "In human hepatoma and renal cell lines BMP7 exposure increased SMAD6 levels, which reduced SMAD2/3-SMAD4 heteromerization." (PMID 34608249, 2021).
hepatocellular carcinoma (continued). "A shift in Smad2/3 phosphorylation from the carboxy terminus to linker sites is a key event determining biological function of TGF-β in colorectal and hepatocellular carcinoma." (PMID 22539990, 2012). "Above all, we found that Smad2/3/4 complex could undergo liquid liquid phase separation to active TAT gene expression, and active caspase-9 to induce hepatoma cell apoptosis through regulating TAT to inhibit HCC progress." (PMID 38769521, 2024). "Taking together, our research explored that Smad2/3/4 complex could undergo LLPS and binds to TAT gene promotor site to upregulate TAT expression, which can active caspase-9 to induce hepatoma cell apoptosis." (PMID 38769521, 2024). "Overexpression of EDIL3 in hepatocellular carcinoma could induce the phosphorylation of SRC, ERK, and SMAD2, leading to the activation of ERK and TGF-β signaling." (PMID 35096599, 2021). "For example, a direct cross talk between Smad3 and STAT3 is bridged by p300 in hepatoma cells, a synergistic action of LIF-induced-Smad1 and BMP2-induced-STAT3 is bridged by p300 in neural cells, and Smad2/3 and STAT3 cooperatively interact in Th17 cell differentiation." (PMID 29963056, 2018). "In the current study, our results showed that JR pretreatment partly blocked TGFβ1-induced phosphorylation of Smad2/3, indicating JR may inhibit TGFβ1-induced EMT in hepatoma cells through Smad2/3-dependent pathway." (PMID 30174709, 2018). "In keeping with our results, in a hepatocellular carcinoma (HCC) cell line, LY2157299 blocked cell migration by activating SMAD2, but independently from TGF-b receptors (TGF-bRs)." (PMID 28873435, 2017). "When PAK3 was overexpressed in Huh7 and HepG2 hepatoma cells, the levels of p-Smad2 and p-Smad3 were significantly increased, while the levels of total Smad2 and Smad3 were almost unchanged, suggesting that PAK3 may act through the Smad-dependent TGF-β pathway to promote EMT in hepatoma cells." (PMID 34976179, 2022). "A recent study found that infiltrating Treg cells could activate Smad2/3 by secreting TGF-β1, greatly triggering EMT in hepatocellular carcinoma (HCC)." (PMID 34576042, 2021). "A previous study reported that Smad3, not Smad2, was the key mediator of TGF-β1-induced apoptosis in Hep3B hepatoma cells." (PMID 31189885, 2019).
Myocardial fibrosis (70 papers, 2015 to 2026). "This study confirmed that prazosin reversed the inhibition of NE on CHIP expression by blocking α1-AR, which helped to further constrain NE-mediated Smad2/3 activation and cardiac fibroblast differentiation, leading to preventing myocardial fibrosis caused by LPS." (PMID 41212462, 2025). "Thus, Smad2/3 induced myocardial fibrosis is an important cause of sudden cardiogenic death in pediatric patients and late heart failure in adults." (PMID 36878974, 2023). "According to our in vitro and in vivo findings, hydrogen inhibits TGF-β1 secretion and activation, suppresses TGF-β1/Smad2/3 pathway, and ultimately ameliorates myocardial fibrosis." (PMID 39775356, 2025). "These macrophages enhance cardiac hypertrophy and stimulate myocardial fibrosis by producing transforming growth factor beta 1 (TGF-β1), proliferating fibroblasts, activating Smad2/3 signaling, and promoting myocardial fibrosis." (PMID 39682749, 2024). "miR-494-3p regulates FBs activation by inhibiting PTEN expression and activating the AKT/Smad2/3/ERK signaling pathway and is closely related to the occurrence and development of myocardial fibrosis caused by stress overloading." (PMID 39228519, 2024). "In contrast, increased activity of the NO-cGMP-PKG pathway attenuates signaling through the SMAD2/3 pathway and prevents the development of myocardial fibrosis." (PMID 38732177, 2024). "This is related to 2-AG inhibiting the protein expression of TGF-β1/Smad2/3 and reducing myocardial fibrosis." (PMID 35305183, 2023). "Overall, besides of positive regulation to myocardial fibrosis by increased expression of SMAD2 and SMAD3, decreased expression of SMAD7 was closely related to collagen deposition, which negatively expedited fibrotic responses in patients with HOCM." (PMID 36878974, 2023). "It activates the Smad2/3 signaling pathway mainly through binding TGF-β receptors to facilitate the myocardial fibrosis process." (PMID 36820397, 2023). "In myocardial infarction studies, activation of Smad2 and Smad3 led to myocardial fibrosis and cardiac remodeling." (PMID 36878974, 2023). "Studies have found that aerobic exercise training reduces myocardial fibrosis by inhibiting the transforming growth factor-β1 (TGF-β1)-Smad2/3 signaling pathway and decreasing Col1 and Col3 protein expression in myocardial infarcted rats." (PMID 36771445, 2023). "It has been reported that when hypertensive myocardial fibrosis occurs, the TGFβ-1-Smad pathway in the myocardium is active, and TGFβ-1 and Smad2/3 are upregulated." (PMID 36818353, 2023). "Both in vitro and in vivo evidence suggests that elevated TGF-β1 levels activate the downstream Smad2/3 pathway, thereby promoting the process of myocardial fibrosis." (PMID 36771445, 2023). "The ability of ISO to cause myocardial fibrosis in rats was demonstrated by the increased TGF-β, collagen III, and phosphorylated Smad2/Smad3 protein levels." (PMID 36964489, 2023). "TGF-β1 exacerbates myocardial fibrosis by binding to receptors, activating Smad2 and 3, and further translocating to the nucleus, up-regulating the expression of genes associated with ECM synthesis, and promoting ECM deposition." (PMID 36820397, 2023). "Myocardial fibrosis is associated with up-regulation of TGF-β1 and the downstream Smad2 and Smad3 proteins, as well as down-regulation of Smad7 expression." (PMID 35279096, 2022). "TMAO can increase the expression of TGFB receptor I (TGFBR1), activate the TGFBR1/Smad2 pathway, and aggravate myocardial fibrosis in mice." (PMID 34925503, 2021). "Taken together, TSF seems to attenuate myocardial fibrosis in KKAy mice by inhibiting TGF-β/Smad2/3 and Wnt/β-catenin signaling pathways." (PMID 34938743, 2021).
Myocardial fibrosis (continued). "tanshinone IIA inhibited myocardial fibrosis by inhibiting TGF-β1-mediated phosphorylation of Smad2/3." (PMID 34925046, 2021). "These authors observed that the fibroblast-specific double deletion of Tgfbr1/2 or Smad2/3 protected from TAC-induced myocardial fibrosis." (PMID 34572061, 2021). "Western blotting showed ALD significantly increased the expression of Smad-2,-3, and-4; these three proteins can promote myocardial fibrosis and play major roles in the TGF-β-Smad signaling pathway." (PMID 27457615, 2016). "In the context of DCM, hyperglycemia can directly stimulate TGF‐β1 expression, leading to phosphorylation of Smad2 and Smad3 in the cytoplasm, which then translocate to the nucleus to induce transcription of fibrosis‐promoting genes, thereby participating in myocardial fibrosis." (PMID 41573701, 2026). "Alleviates myocardial fibrosis (via inhibition of β1‐AR/TGF‐β1/Smad2 signaling)." (PMID 40634132, 2025). "In summary, the therapeutic mechanism of vericiguat may be to inhibit myocardial fibrosis by regulating the TGF-β1/Smad2/3 pathway." (PMID 40680000, 2025). "Overall, the therapeutic mechanism of vericiguat may be to inhibit myocardial fibrosis by inhibiting the TGF-β1/Smad2/3 pathway." (PMID 40680000, 2025). "Here, we also detected the protein levels of the TGFβ-Smad signaling pathway (TGFβR2, p-Smad2, and p-Smad3) and myocardial fibrosis markers (Col1α1, Col1, α-SMA) in fibroblasts after 10 ng/mL TGFβ plus miR-194-3p mimic, miR-194-3p inhibitor and TGFβR2 siRNA treatment." (PMID 39346544, 2024). "In addition to inhibiting myocardial fibrosis through TGF-β1/Smad2 signaling pathway, icariin can also inhibit myocardial fibrosis and delay the progression of HF by regulating the protein expression of α-smooth muscle actin (α-SMA) and MMPs/MMP-1." (PMID 38444481, 2024). "It has been suggested that low apelin levels may interfere with AF susceptibility through elevated atrial NADPH-dependent oxidative stress and the TGF-β/Smad2/α-SMA pathway associated with mitochondrial dysfunction and myocardial fibrosis." (PMID 37239123, 2023). "2-AG could effectively inhibit the up-regulation of TGF-β1 and Smad2/3, reduce myocardial fibrosis, and ultimately improve cardiac function in diabetic mice." (PMID 35305183, 2023). "Previous studies have suggested that irisin could be a promising therapy against myocardial fibrosis as irisin attenuates angiotensin II-induced cardiac fibrosis via the Nrf2 mediated inhibition of the ROS/TGFβ1/Smad3/Smad2 (Smad2/3) signaling axis." (PMID 36135450, 2022). "Icariin (ICA) suppresses the TGF-β1/Smad2 pathway in myocardial fibrosis in rats." (PMID 33335559, 2020). "Thus, our findings suggest that the activation of TRPM7/Smad2 signaling by Ang II is an important mechanism leading to myocardial fibrosis in SAN tissues in SSS rats, indicating that TRPM7 is a potentially therapeutic target for SSS treatment." (PMID 29511803, 2018). "Additionally, it inhibits TGFβ1/Smad2 signaling and alleviates myocardial fibrosis in rats." (PMID 33335559, 2020). "Increased expressions of SMAD2 and SMAD3 contributed to myocardial fibrosis in patients with HOCM, which happened early in childhood and continued through adulthood." (PMID 36878974, 2023). "A role for SMAD-2 and SMAD-3 signaling in fibrosis has also been suggested in post-infarction myocardial fibrosis." (PMID 36232788, 2022). "In the KKAy mouse model with myocardial fibrosis, we found the overexpression of collagens I and III and α-SMA, as well as the activation of TGF-β1 and p-Smad2/3 and the reduction of Smad7." (PMID 34938743, 2021). "In conclusion, the present study revealed that LQ ameliorated ISO-induced myocardial fibrosis in mice and inhibited the apoptosis of cardiomyocytes in vitro by inhibiting the TGF-β1/Smad2 and AKT/ERK signaling pathways." (PMID 34328199, 2021).